RN7SL58P (RNA, 7SL, cytoplasmic 58, pseudogene)
Gene: Miscellaneous RNA gene on chromosome 5 (18,547,312 to 18,547,605, forward strand). Ensembl gene ENSG00000241552.
Homologues: Orthologues: chimpanzee Metazoa_SRP (95% identical), macaque Metazoa_SRP (91% identical). Paralogues in human: RN7SL1 (81% identical), RN7SL2 (80% identical), RN7SL3 (79% identical), RN7SL45P (79% identical), RN7SL803P (79% identical), RN7SL492P (78% identical), RN7SL118P (78% identical), RN7SL322P (78% identical), RN7SL113P (78% identical), RN7SL451P (78% identical), RN7SL478P (78% identical), RN7SL680P (78% identical), and 704 more.